ZNF24 (zinc finger protein 24)
Diseases named in the same sentence as ZNF24 in open-access papers (continued):
Sharing a sentence is not in itself a finding about the gene and the disease.
tumor (16 papers, 2009 to 2026). "For the first time, ZNF24 was reported to be associated with tumor invasion and metastasis, but the effects of ZNF24 on GC cells have not been established." (PMID 26317898, 2015). "The expression of YOD1 and ZNF24 was significantly downregulated in tumor tissues, with a strong correlation between them." (PMID 40274778, 2025). "Conversely, tumor-suppressive ZFPs like ZNF24 and ZNF545 inhibit tumor growth by inducing cell cycle arrest and apoptosis." (PMID 41614761, 2025). "Overall, we conclude that YOD1 acts as a tumor suppression factor by attenuating tumor growth and metastasis through the ZNF24/VEGFA pathway in ccRCC." (PMID 40274778, 2025). "Knockdown of YOD1 markedly promoted subcutaneous tumor growth and lung metastasis, and these effects were reversed by ZNF24 overexpression." (PMID 40274778, 2025). "To further validate these findings, we performed immunohistochemical staining for YOD1 and ZNF24 in a tumor microarray for ccRCC (cohort 1), which consisted of 80 paired tumor and normal tissue samples and an additional 110 surgical tumor samples (cohort 2)." (PMID 40274778, 2025). "Previous studies have shown that ZNF24 can inhibit tumor angiogenesis by reducing the expression of VEGF-A." (PMID 39349443, 2024). "Research shows that upregulated ZNF24 increases tumor volume, migration and invasion through EMT process." (PMID 38717954, 2024). "Examination of hematoxylin and eosin (H&E)-stained lung tissue sections revealed retroviral expression of ZNF24 significantly inhibited tumor formation in lungs of KC-Z." (PMID 36457047, 2022). "In comparison to control group, we detected significantly more tumor nodules, tumor burdens, larger tumor nodules and tumor size and amount of stage 4 tumors in ZNF24 knockout mice after 6 months of nasal inhalation of lentivirus." (PMID 36457047, 2022). "Recent studies have found that ZNF24 is a pleiotropic factor involved in many critical biologic events and pathways, such as tumor progression and angiogenesis, brain development, DNA replication, and DNA damage response." (PMID 28968968, 2017). "Overexpression of miR-940 promotes GC cell migration and invasion by binding and downregulating the tumor-suppressing gene ZNF24." (PMID 26317898, 2015). "A significantly higher level of ZNF24 was detected in non-tumor tissues than in corresponding tumor samples." (PMID 26317898, 2015). "ZNF24 was a vital zinc finger transcription factor containing DNA binding domain and played an important role in tumor progression and angiogenesis." (PMID 26317898, 2015). "Decreased ZNF24 expression significantly correlated with aggressive tumor phenotypes, such as larger tumor size, lymph mode metastasis, and advanced stage." (PMID 26317898, 2015). "BMI1 induces the ubiquitination of histone H2A, which suppresses the expression of zinc finger protein 24 and decreases the secretion of vascular endothelial growth factor A, thereby promoting tumor angiogenesis and providing support for tumor cell proliferation and metastasis." (PMID 41268614, 2026). "Both YOD1 and ZNF24 exhibited low expression in the majority of the tumor specimens." (PMID 40274778, 2025). "Since RAS signaling is closely related to malignant tumor proliferation, we hypothesized that ZNF24 may promote the progression of KRAS mutant LUAD by upregulating SLC7A5 protein expression." (PMID 36505791, 2022). "Then, the expression levels of ZNF24 and SLC7A5 were detected in 16 selected KRAS mutation tumor tissues and KRAS wild-type tumor tissues from the samples by qPCR and Western blot analysis, and we found that the expression levels of ZNF24 and SLC7A5 were both increased in KRAS mutation patients." (PMID 36505791, 2022). "Taken together, ZNF24 might be a potential tumor suppressor gene in GC." (PMID 26317898, 2015).
tumor (continued). "As ZNF24 has been proven to promote the growth of SLC7A5-mediated KRAS mutant LUAD cells in vitro, we established a nude mouse transplanted tumor model for in vivo experimental verification." (PMID 36505791, 2022). "ZNF24, a crucial transcriptional repressor of VEGFA, binds to an 11 bp fragment in the proximal promoter region on the VEGFA gene, inhibiting its transcription and subsequently impeding tumor growth and invasion." (PMID 40274778, 2025). "The strong inverse correlation between ZNF24 and MMP2 expression was observed in vitro and in vivo, suggesting that ZNF24 may be a potential tumor suppressor that may negatively regulate MMP2 expression in CRC." (PMID 40520987, 2025). "In addition, knockdown of ZNF24 reduced ki-67 positive cells in transplanted tumors, while SLC7A5 overexpression after ZNF24 knockdown partially reversed tumor suppression, and ki-67 positive cells were increased." (PMID 36505791, 2022). "By plotting the tumor growth curve and comparing tumor volumes, we observed that knocking down ZNF24 significantly inhibited the growth of A549 cell-transplanted tumors, while SLC7A5 overexpression after ZNF24 knockdown partially reversed tumor inhibition." (PMID 36505791, 2022). "In addition, since the upregulation of SLC7A5 is closely related to abnormal amino acid metabolism and immune evasion, in this study, we identified the regulatory mechanism of ZNF24 on SLC7A5, which is crucial for the blockade of tumor metabolism and immunotherapy of KRAS mutant LUAD." (PMID 36505791, 2022).
cancer (15 papers, 2009 to 2025). A tumor composed of atypical neoplastic, often pleomorphic cells that invade other tissues. "Although studies have explored the paradoxical role of ZNF24 in the initiation and development processes of various cancers, the precise role and underlying mechanism of ZNF24 in CRC remain largely unclear." (PMID 40520987, 2025). "Research has demonstrated that ZNF24 functions as a transcriptional inhibitor in various cancers by repressing VEGFA transcription." (PMID 40274778, 2025). "Our previous analysis has revealed that ZNF24 is a pleiotropic factor that has a role in hematopoiesis, brain development, and cancers." (PMID 40520987, 2025). "The zinc finger protein 24 gene (ZNF24, also known as ZNF191 and KOX17) is related to ZNF191, which probably is associated with some hereditary diseases and cancers." (PMID 22545106, 2012). "In addition to regulating normal cells, ZNF24 has been shown to have significant effects on the initiation and progression of cancer and angiogenesis." (PMID 38127891, 2023). "Third, this previous study indicated that miR-490 could inhibit BC progression via regulating its target gene ZNF24, while our further experiments showed that miR-940 could promote cancer progression through regulating FOXO3." (PMID 32840296, 2020). "Additionally, ZNF24 has also been shown to inhibit cell proliferation in cancers." (PMID 40274778, 2025). "As expected, ZNF24 mRNA and protein levels were down-regulated in CRC compared with that of adjacent carcinoma, while the expression level of MMP2 in CRC was significantly up-regulated compared with that of adjacent carcinoma." (PMID 40520987, 2025). "Based on the literatures included in PubMed, GPR12, ITM2B, ZNF24, and NSL1 were selected as the candidate targets due to the low expressions in various cancers." (PMID 37789353, 2023). "It was reported in many studies that miR-940 was highly expressed in normal tissues compared with tumors, and miR-940 was shown to inhibit the migratory and invasive potential of cancer cells by suppressing CXCR2, MIEN1, MyD88, Nestin, and ZNF24." (PMID 28423620, 2017). "Three genes ASF1A, RASGRP3 and ZNF24 were not covered by any representative term and none of them is an NCG cancer gene." (PMID 34504716, 2021).
infection (2 papers, 2023 to 2024). The state of being infected such as from the introduction of a foreign agent such as serum, vaccine, antigenic substance or organism. "We further identify several TFs which are not, in healthy cells, specific to any immune cell type, but are predicted to have cell type-specific changes to TF activity during infection (e.g., HMBOX1, ZNF24, ZNF691)." (PMID 38238840, 2024).
ZNF24 also shares sentences with these, for which no sentence is quoted: liver cancer (2 papers); acute promyelocytic leukemia (1); bladder cancer (1); cervical cancer (1); clear cell renal carcinoma (1); Gliosis (1); leukodystrophies (1); mucinous adenocarcinoma (1); non-small cell lung carcinoma (1); oral mucositis (1).